ANAPC1P1 (ANAPC1 pseudogene 1)
Gene: Transcribed unprocessed pseudogene on chromosome 2 (86,871,301 to 86,912,978, forward strand). Ensembl gene ENSG00000233673.
Diseases named in the same sentence as ANAPC1P1 in open-access papers:
ANAPC1P1 is named in the same sentence as 3 diseases in open-access papers, as found by Europe PMC text mining. Sharing a sentence is not in itself a finding about the gene and the disease. The quoted sentences say what the papers report.
cervical cancer (1 paper, 2020). A primary or metastatic malignant neoplasm involving the cervix. "Of the 11 significant lncRNAs, only LINC00675 and HNF1A-AS1 have been reported in cervical cancer cells and the left 9 lncRNAs (MIR194-2HG, LINC00675, LOC101060400, LOC105371049, SSTR5-AS1, C8orf34-AS1, PPIGP1, KCCAT333, LINC01541, and ANAPC1P1) were newly identified in this study." (PMID 33024199, 2020).
ANAPC1P1 also shares sentences with these, for which no sentence is quoted: cancer (1 paper); tumor (1).